PALB2 (partner and localizer of BRCA2)
Diseases named in the same sentence as PALB2 in open-access papers (continued):
Sharing a sentence is not in itself a finding about the gene and the disease.
tumor (continued). "PALB2 and ATM validate as HGSOC predisposition genes, with 6/8 germline carrier tumours exhibiting biallelic inactivation accompanied by characteristic mutational signatures." (PMID 39794353, 2025). "In control samples, fluorescence intensity exclusive for IQGAP1 exhibited a relative intensity of 12.5 ± 2.5% in control tumor cells, 6.5 ± 1.5% specific for PALB2 alone, and co-localization of both markers was observed in only 5.0 ± 1.0% of signals." (PMID 40868059, 2025). "Mutational signature analysis using the SIGNAL Ovary signature set33 was performed for tumours with demonstrable loss or inactivation of the wildtype allele in multiple samples (three PALB2 and ATM tumours each)." (PMID 39794353, 2025). "IQGAP-specific immunofluorescence at medium- to high-level intensity is presented in cytosol and plasma membrane, frequently colocalizing with PALB2 (merging) in some tumor areas (PCC = 0.67 p < 0.05)." (PMID 40868059, 2025). "Immunofluorescence analysis revealed a robust expression of PALB2 in both the cytoplasm and nuclei of tumor cells from control cases, in line with its known role in DNA repair through homologous recombination." (PMID 40868059, 2025). "The tumor suppressor PALB2 functions with the BRCA1 and BRCA2 proteins to maintain genomic integrity by homologous recombination." (PMID 39745016, 2025). "In the control case, PALB2 exhibited specific fluorescence at high intensity in cytosol and to a lesser extent in the nuclei of tumor cells." (PMID 40868059, 2025). "To summarize, accumulating but still preliminary evidence indicates that BRCA- or PALB2-mutated PDAC harbors a unique and relatively immune-permissive tumor microenvironment." (PMID 40426860, 2025). "In summary, PALB2 and ATM were the only proposed genes displaying consistent, verifiable somatic biallelic inactivation across multiple tumour samples from germline variant carriers." (PMID 39794353, 2025). "Remarkably, PALB2 mutant samples displayed a more homogeneous tumor cell population with strong peripheral IQGAP1 expression and high colocalization with β-tubulin." (PMID 40868059, 2025). "All three PALB2 tumours with biallelic inactivation had calculated or estimated high HRD scores, whereas other tumours with biallelic inactivation showed no consistent pattern in this regard." (PMID 39794353, 2025). "The tumor suppressor PALB2 is a key player in the homologous recombination (HR) pathway, functionally connecting BRCA proteins at the DNA damage site." (PMID 39745016, 2025). "NCCN also suggests biomarker-guided treatments for tumor mutation burden-high and RET fusion-positive tumors, and ESMO suggests treatment for patients with BRCA1/2 or PALB2 mutations." (PMID 38838500, 2024). "As a crucial tumor suppressor gene involved in the homologous recombination (HR) pathway, PALB2 acts as a mediator between BRCA1 and the BRCA/RAD51 complex." (PMID 38920970, 2024). "In samples of our patient’s buccal swab, peripheral blood, and tumor tissue, a pathogenic variant in the partner and localizer of BRCA2 (PALB2) gene was found." (PMID 38817905, 2024). "Variants in 5 genes (RPN1, CDKN2A, HRAS, PALB2, CBFA2T3) have been identified in 32 individuals with tumor from the extended cohort and classified as pathogenic, likely pathogenic, and VUS." (PMID 36845707, 2023). "For example, the PALB2 tumor suppressor plays key roles in DNA repair and has been implicated in redox homeostasis, thereby promoting antioxidant gene expression." (PMID 37676416, 2023).
tumor (continued). "At the next stage of the work, in the formed sample of patients, using the Accel-Amplicon BRCA1, BRCA2, and PALB2 panel, tumor samples were screened before and after chemotherapy for the presence of mutations in the studied genes." (PMID 37628606, 2023). "Two patients had a tumor with a BRCA1 mutation, one had BRCA1 and FANCA mutations, one had a PALB2 mutation, one had a BRCA1 VUS, and one had a BRCA2 VUS." (PMID 37173992, 2023). "In a study of patients with tumor CGP-identified mutations in moderate risk breast and ovarian CSGs (ATM, BRIP1, CHEK2, PALB2, RAD51C, and RAD51D), 24% of patients with germline variants would not have met criteria for germline testing." (PMID 37568048, 2023). "The PALB2 gene product is a tumor suppressor and interacts with BRCA1 and BRCA2 to form a BRCA complex during double-strand break repair." (PMID 36359225, 2022). "The sensitivity of tumors with HRR mutations (HRRm), including BRCA1, BRCA2, PALB2, and RAD51C, to PARPi has been reported in preclinical research, as well as clinically, across tumor types." (PMID 36970052, 2022). "The tumor suppressor BRCA1 interacts with PALB2 and BRCA2, and localizes to repair foci at DNA lesions similarly to MR64–66." (PMID 35501303, 2022). "The PALB2 tumor suppressor plays key roles in DNA repair and has been implicated in redox homeostasis." (PMID 35404932, 2022). "Another 18 tumour-related genes such as NCOR2 and PALB2 were found to be mutated in BTG and PTCb only." (PMID 36686473, 2022). "The tumour suppressor PALB2 stimulates RAD51-mediated homologous recombination (HR) repair of DNA damage, whilst its steady-state association with active genes protects these loci from replication stress." (PMID 36269050, 2022). "All patients with germline mutations in PALB2(gPALB2; encoding partner and localizer of BRCA2) had treatment-associated tumor regression." (PMID 36253484, 2022). "The tumor suppressor NOTCH1 and the DNA strand break repair gene PALB2 were more frequently mutated in early onset tumors." (PMID 35003350, 2021). "Of patients with pathogenic variants in BRCA2 or PALB2, 60% of AA patients (12/20) versus 12% of EA patients (3/25) presented with TNBC versus any other tumor subtype (P = 0.001)." (PMID 33479248, 2021). "To understand why co-ablation of Brca1 with Palb2 led to delayed tumor formation, we analyzed markers of DNA damage, oxidative stress, and apoptosis in Brca1 and Palb2 single and double deletion mammary glands." (PMID 33893322, 2021). "Further and more in-depth studies are required to define the complementary functions of BRCA1 and PALB2/BRCA2 in tumor suppression." (PMID 33893322, 2021). "TBCRC 048 evaluated the role of olaparib in homologous recombination deficient tumours due to genomic alterations other than germline BRCA1/2 mutations; clinically relevant activity was reported in patients with germline PALB2 and somatic BRCA1/2 mutations." (PMID 33520003, 2021). "The tumour suppressor PALB2 mediates the physical interaction of BRCA2 with the COOH-terminal fragment of BRCA1." (PMID 34771713, 2021). "Lastly, the PALB2 missense variant (c.2606C > T;p.Ser869Phe) was present in LLS18, whose respective tumor showed the largest indel burden." (PMID 33809179, 2021). "Many mouse models have been generated to study the function of BRCA1, BRCA2, and PALB2 in development and tumor suppression." (PMID 33893322, 2021). "Overall, 28% of carriers of HR-related gene variants had a presence of HR-deficiency associated tumor mutational signature, which increased to 86% of carriers when only well-recognized HR genes (BRCA1, PALB2 and RAD51C) were included." (PMID 33917078, 2021).
tumor (continued). "The fact that both mammary and overall tumor development were most efficient in P2p53 mice also implies that PALB2 is at least as critical a tumor suppressor as BRCA1 and BRCA2." (PMID 33893322, 2021). "In summary, PALB2 tumours show the homologous recombination deficiencies characteristic of BRCA1 and BRCA2 tumours, and highlight the potential clinical relevance of PALB2 mutational status in guiding therapeutic choices." (PMID 33893315, 2021). "In this study, we describe molecular characteristics of tumours with either germline or somatic alterations in PALB2." (PMID 33893315, 2021). "Both germline and tumor DNA were obtained from an affected relative of CABR61 (with the germline MRE11A splice site mutation enriched in tumor) and CABR95 (with the germline PALB2 pathogenic mutation inducing a frameshift and enriched in the tumor)." (PMID 32295625, 2020). "Four variants showed LOH in the tumor specimen (ATM c.4709T>C; CHEK2 c.1036C>T; PALB2 c.1001A>G, and RAD50 c.281T>C), which is an indication of pathogenicity." (PMID 33134171, 2020). "The results of tumor analyses were confirmatory for PALB2 (5 ASTs in 5 tumor samples) and supportive for ATM (2 LOHs in 3 tumors), but the other genes contributed less (limited analyses)." (PMID 32566746, 2020). "Four variants of uncertain significance showed loss of heterozygosity in the tumor (ATM c.4709T>C; CHEK2 c.1036C>T; PALB2 c.1001A>G, and RAD50 c.281T>C), which is an indication of pathogenicity." (PMID 33134171, 2020). "Palb2-, Brca1- or Brca2- deleted tumor cells exhibit dramatically elevated sensitivity to DNA damaging drugs compared to KPC cells in vitro." (PMID 31877165, 2019). "Whole body deletion of the mouse Palb2 gene results in early embryonic lethality similarly to the Brca1 and Brca2 knock-out animals, indicating that all three tumor suppressor gene products, Palb2, Brca1 and Brca2 are essential for embryonic viability." (PMID 31877165, 2019). "Rad50, Rad51, Rad54b, Mre11a, Palb2, Brca1 and Bard1 all showed significantly higher expression in resistant tumours compared to responding tumours (p = 0.05, p < 0.001, p < 0.001, p < 0.001, p = 0.002, p < 0.001 and p = 0.012 respectively)." (PMID 31080552, 2019). "Most of the Palb2-KPC mice have tumor developing in the head of the pancreas where they are more likely to grow into the bile-duct." (PMID 31877165, 2019). "As expected, disruption of Palb2 and Brca1/2 sensitized tumor cells to DNA damaging agents in vitro and in vivo." (PMID 31877165, 2019). "Palb2-, Brca1- or Brca2- deficient tumor cells in comparison to KPC or Palb2flox/+-KPC tumor cells are exquisitely sensitive to DNA damage inducing agents, including Olaparib, MMC and Cisplatin." (PMID 31877165, 2019). "We characterized the PALB2 deleterious variant in the PARPi‐sensitive PDX093, as it was heterozygous in the tumor." (PMID 30377213, 2018). "Under normal conditions, PALB2 functions as a tumor suppressor similarly to BRCA1 and BRCA2 in maintaining the genome stability and cellular homeostasis." (PMID 29643976, 2018). "PALB2 is a DNA maintenance gene, where the encoded protein binds to and colocalizes with BRCA2 in nuclear foci, and plays a role of tumor suppression." (PMID 29212173, 2017). "However, it is unknown whether PALB2 tumour suppressor function requires its chromatin association." (PMID 29387807, 2017). "This resulted in a considerably milder clinical phenotype with increased longevity compared with biallelic PALB2 null patients and an altered tumour spectrum towards development of lymphoid malignancies." (PMID 26990772, 2016). "Taken together, these observations have raised concerns over the significance of the interaction between BRCA2 and PALB2, especially on the tumor suppressor function of BRCA2." (PMID 27490902, 2016). "This increased tumor predisposition of Brca2G25R/KO mice suggests that the physical interaction of BRCA2 with PALB2 is critical for their tumor suppressor function." (PMID 27490902, 2016).
tumor (continued). "At PALB2, the tumor-derived DNA had elevated methylation across 12 promoter associated probes (Δβ 4.67%; adj." (PMID 27902704, 2016). "We conclude that not only are BRCA2 and PALB2 required for tumor suppression, their physical interaction is equally important." (PMID 27490902, 2016). "For PALB2, 40 out of 43 most tumor-derived DNA samples had a higher level of methylation at two promoter probes (cg08762306 and cg05002041) when compared with the average blood-derived DNA methylation." (PMID 27902704, 2016). "Significant, tumour-specific loss of heterozygosity occurs in nine genes (ATM, BAP1, BRCA1/2, BRIP1, FANCM, PALB2 and RAD51C/D)." (PMID 26689913, 2015). "We find that a BRCA2 fusion peptide deleted for the DNA binding domain and active in HR is completely dependent on interaction with the PALB2 tumor suppressor for activity." (PMID 22194698, 2011). "Results showed HMMR and PALB2 were significantly overexpressed in CRC tumor vs. normal tissues." (PMID 41602397, 2026). "In ccRCC, PALB2 pathogenic mutations are infrequent to rare in tumor or germline assessments; the existing literature does not endorse a consistent prognostic significance." (PMID 41440218, 2025). "Our combined findings suggest that truncated PALB2 may exert pleiotropic effects on tumor cell behavior by simultaneously modulating genomic maintenance and cytoskeletal organization, probably by moonlighting the roles of these proteins." (PMID 40868059, 2025). "Like BRCA1/2, germline PALB2 mutations cause HRD and genomic instability in tumors, which enable DNA damage and may affect the aggressiveness of the tumor." (PMID 41374970, 2025). "The tumor diameter was reported in 31 (62.0%) PALB2 carriers." (PMID 40428378, 2025). "The index patient in family A06 (A06‐01) carried variants in several classical tumor suppressor genes, including two different variants in MLH1 (A441T and the K618A), a variant in PALB2 (L939W) and several variants in ATM and ATR, all classified as VUS or benign." (PMID 40072281, 2025). "Of these, one PALB2‐mutant tumor harbored a GIS ≥42, whereas all other cases did show a GIS <42." (PMID 40278800, 2025). "However, to date, there is a lack of comprehensive data describing other tumor characteristics such as histological subtype and tumor size and stage in PALB2, RAD51C, and RAD51D GPV carriers." (PMID 40428378, 2025). "For the 2 patients with germline variants in PALB2, one showed expression of their heterozygous PALB2 variant in the tumor RNA, indicating that there was no second hit in the tumor." (PMID 40072012, 2025). "Given the complexity of HRD biomarkers, key assay features include the selection of HRR genes (BRCA1, BRCA2, PALB2, RAD51C, RAD51D), definitions of genomic scars (LOH, TAI, LST), mutational signatures analyzed, use of comparator samples, and tumor-specific HRD score calculations." (PMID 40864792, 2025). "Notably, Bayogenin displayed lower average RMSF values compared to Olaparib, particularly within the PALB2 complex, highlighting its role in stabilizing critical protein regions involved in DNA repair and tumor suppression." (PMID 40739477, 2025). "The variant allele frequency in tumor tissue was high, suggesting that our patient’s TNBC developed predominantly due to the PALB2 variant; however, previous management of her B-ALL could also have contributed to the development of TNBC." (PMID 38817905, 2024). "Furthermore, to evaluate the role of neoantigen-specific CD8+ T cells in tumor immunity, they implanted WHIM30 tumor sections into immune-compromised mice and adoptively transferred autologous PBMCs stimulated with PALB2, ROBO3, or CMV peptides." (PMID 38920970, 2024).
tumor (continued). "MORF4L1 interacts with the BRCA multiprotein complex, and thereby mediates DNA damage response and repair of DNA double-strand breaks, having therefore a potential tumour suppressor role, through interaction with PALB2 and BRCA, members of the DNA damage repair signalling pathway." (PMID 39267821, 2024). "Notably, the somatic NGS panel can offer other information with clinical relevance, such as the presence of mutations in BRCA1, BRCA2, PALB2, ERBB2, and ESR1, in addition to molecular changes that can be treated with tumor-agnostic therapies." (PMID 38952553, 2024). "Additionally, nearly significant differences (p = 0.0503) were seen in the probability of the age of tumor onset between PALB2 P/LP carriers and patients with normal genotypes." (PMID 37686625, 2023). "Furthermore, tumours showing homologous recombination deficiency, due to loss of BRCA1, BRCA2, PALB2 and CHEK2 function, have been shown to be especially sensitive to platinum-based chemotherapeutics and PARP inhibition." (PMID 36831687, 2023). "From a total of 6830 tumor samples from 6527 individual patients that underwent tumor DNA sequencing, 584 unique tumor variants were identified in the gene list of interest (ATM, BRCA1, BRCA2, MLH1, MSH1, MSH6, PALB2 and PMS2) from 503 unique tumor samples/patients during the study period." (PMID 36261688, 2023). "Genes with fewer than 10 tumor variants identified (MLH1, PALB2, PMS2) had more variable frequencies of being germline (likely due to low n value for each of these genes), but collectively they had a similar percentage of being germline when combined as a single group (40%)." (PMID 36261688, 2023). "Afterwards, sensitivity to PARPi has been proved in tumor with loss of other tumor suppressor DNA repair proteins (e.g., ATR, ATM, RAD51, CHEK1/2, and PALB2), suggesting the validity of this therapeutic strategy also in patients intrinsically deficient in HR without BRCA1/2 mutations." (PMID 36793600, 2023). "Additionally, some of these genes, such as Poli (error-prone polymerase involved in DNA repair), Rac1 (cell growth regulator), and Palb2 (tumor suppressor) were observed on eccDNA in CHO cells." (PMID 36681715, 2023). "Additionally, some DGC patients tested negative for CDH1/CTNNA1 gene but had pathogenic variants in related tumor susceptibility genes, such as BRCA2, ATM, SDHB, PRSS1, MSR1, STK11, and PALB2." (PMID 37393258, 2023). "However, the median age of tumor onset was 44 years in PALB2 P/LP carriers versus wild-type patients where it was 48 years (p = 0.0503)." (PMID 37686625, 2023). "Only 0.80% (n = 1) tumor was found to have PALB2, while 18.60% (n = 22) were found to have BAP1." (PMID 36831055, 2023). "Here, we review the molecular features and hereditary tumor risk associated with several moderate-penetrance genes in EOC that are involved in the homologous recombination repair pathway, i.e., ATM, BRIP1, NBN, PALB2, and RAD51C/D." (PMID 36233090, 2022). "Furthermore, germline mutations in BRCA1/2 HR pathway interaction partners, PALB2 and RAD51C, were also shown to confer a tumor mutation signature enriched for HR deficiency in four cases of GC." (PMID 36497436, 2022). "After adjustment for tumor grade and molecular subtype, a linearregression model with rank transformation showed that the DNA expression of 2genes (PALB2 and ERCC1) assessed in pre-NACTbiopsies was lower in the pCR group than in the non-pCR group (P=0.014 andP=0.040, respectively)." (PMID 35293552, 2022). "This new discovery adds to the repertoire of PALB2 functions and may have implications in not only neurodegeneration but also tumor suppression." (PMID 35404932, 2022). "Recent studies have found that germline mutations of PALB2 exist in families with BC, indicating that PALB2 may be a tumor suppressor for FBC." (PMID 34926254, 2021).